ASPA (aspartoacylase)
Diseases named in the same sentence as ASPA in open-access papers (continued):
Sharing a sentence is not in itself a finding about the gene and the disease.
leukodystrophy (18 papers, 2010 to 2024). Leukodystrophies are a group of rare, progressive, metabolic, genetic diseases that affect the brain, spinal cord and often the peripheral nerves. "CD is a fatal leukodystrophy caused by mutation in the ASPA gene, which leads to a deficiency in the ASPA enzymatic activity." (PMID 37867939, 2023). "CD is a rare leukodystrophy resulting in neurodegeneration that occurs after a LoF mutation in the gene encoding aspartoacylase (ASPA)." (PMID 34690692, 2021). "Mutations affecting genes that encode classical myelin proteins including PLP, CNP, MAG, TUBB4, and ASPA cause severe neurological disorders including hypomyelinating leukodystrophies (HLD) and spastic paraplegias (SPG)." (PMID 32973451, 2020). "Notably, only one study developed a 3D culture protocol specifically tailored for CD, a rare leukodystrophy resulting from the loss of function in the aspartoacylase (ASPA) gene, which affects altered ASPA-expressing mature oligodendrocytes of the CNS." (PMID 38727281, 2024). "Cellular mechanisms attributed to hypomyelination in leukodystrophies include contributions to lipid metabolism and myelin biogenesis by various organelles, such as lysosomes, peroxisomes, and mitochondria, as well as enzymes like ASPA." (PMID 36003149, 2022).
schizophrenia (3 papers, 2009 to 2019). A major psychotic disorder characterized by abnormalities in the perception or expression of reality. "More recently, we have shown upregulation of the ASPA enzyme, important in white matter maintenance, in schizophrenia." (PMID 19457239, 2009).
Tremor (3 papers, 2011 to 2024). An unintentional, oscillating to-and-fro muscle movement about a joint axis. "The tremor rat carries a deletion spanning at least 200 kb including the four genes, encoding an olfactory receptor, ASPA, the vanilloid receptor subtype I, and the Ca2+/calmodulin-dependent protein kinase IV." (PMID 38582917, 2024). "When working with the tremor rat model, it is hard to attribute phenotypes specifically to ASPA-deficiency rather than other effects of the deletion." (PMID 38582917, 2024). "However, aspalacZ/lacZ sciatic nerve tissue showed no gross abnormalities (our unpublished results) confirming a report on the normal PNS of the spontaneous ASPA-null tremor rat." (PMID 21625469, 2011).
brain tumors (2 papers, 2017 to 2018). "NAA can be hydrolyzed by aspartoacylase (ASPA) to produce aspartate and acetate which was recently identified as a major bioenergetic substrate in brain tumors." (PMID 29054837, 2017).
developmental delay (2 papers, 2017 to 2024). "This condition, caused by aspartoacylase deficiency, leads to an accumulation of N-acetyl-L-aspartic acid (NAA), resulting in severe motor impairment, muscle tone abnormalities, and developmental delays." (PMID 39524158, 2024).
gastric cancer (2 papers, 2023 to 2025). A primary or metastatic malignant neoplasm involving the stomach. "The knockdown and overexpression of ASPA was found to affect the proliferation and invasion ability of gastric cancer (GC)." (PMID 37391709, 2023).
glioma (2 papers, 2013 to 2023). A benign or malignant brain and spinal cord tumor that arises from glial cells (astrocytes, oligodendrocytes, ependymal cells). "The corresponding author wishes to thank Professor Dylan R. Edwards and Dr. Caroline J. Pennington (University of East Anglia School of Biological Sciences, Norwich UK) for the fabulous sabbatical experience performing the TLDA-based degradome profiling that identified ASPA dysregulation in glioma." (PMID 24278309, 2013). "Moreover, NAA catalysis requires ASPA, which is decreased in glioma." (PMID 24278309, 2013).
neuroblastoma (2 papers, 2023). Neuroblastoma (NB) is the most common solid, extracranial childhood tumor. "Several studies have confirmed that the expression of ASPA is decreased in tumours (prostate cancer, glioblastoma, neuroblastoma) and is correlated with poor prognosis (glioblastoma, neuroblastoma)." (PMID 37391709, 2023). "Only one study has investigated the ASPA level and prognosis of cancer in neuroblastoma patients." (PMID 37271807, 2023).
oligodendroglioma (2 papers, 2013 to 2020). A well-differentiated (WHO grade II), diffusely infiltrating neuroglial tumor, typically located in the cerebral hemispheres. "While ASPA protein levels are significantly reduced in oligodendroglioma and astrocytoma tumors relative to normal brain, ASPA levels in oligodendroglioma-derived cells in vitro are comparable to Oli-Neu OPCs." (PMID 24278309, 2013). "It is noteworthy that ACSS2 was also found to be colocalized with the enzyme aspartoacylase (ASPA; discussed in more detail in section “Local Acetate Production From Acetylated Metabolites”) in the nuclei of oligodendroglioma-derived cells." (PMID 33281616, 2020). "N-acetyl-L-aspartate (NAA), the primary storage form of acetate in the brain, and aspartoacylase (ASPA), the enzyme responsible for NAA catalysis to generate acetate and ultimately acetyl-Coenzyme A for histone acetylation, are reduced in oligodendroglioma." (PMID 24278309, 2013). "For example, in Oli-Neu cells, ASPA levels were increased with time in culture even though CNPase levels did not increase, while in human oligodendroglioma cells, ASPA levels did not change even though CNPase levels increased." (PMID 24278309, 2013).
aspergillosis (1 paper, 2023). Aspergillosis is an infection, growth, or allergic response caused by the Aspergillus fungus. "AspA is important for establishment of virulence in an immunocompetent murine model of aspergillosis." (PMID 37790311, 2023).
cerebral infarction (1 paper, 2010). An ischemic condition of the brain, producing a persistent focal neurological deficit in the area of distribution of the cerebral arteries. "For example, NAA decreases gradually after the development of cerebral infarction where it is broken down into aspartate and acetate by the enzyme aspartoacylase." (PMID 20567596, 2010).
dyspepsia (1 paper, 2019). An uncomfortable, often painful feeling in the stomach, resulting from impaired digestion. "Out of 59 aspA-positive strains, 34 isolates (57.62%) were from nonulcer dyspepsia patients, and 25 isolates (42.38%) were from patients diagnosed with peptic ulcer disease." (PMID 31312620, 2019). "The frequency of aspA (71.95%) (p<0.0001) was significantly higher compared to the frequency of babA (19.51%), homB (3.65%), and sabA (7.31%) in nonulcer dyspepsia and peptic ulcer patients." (PMID 31312620, 2019).
gastric ulcer (1 paper, 2022). An ulcerated lesion in the mucosal surface of the stomach. "To confirm the role of ASPA in the CeA in the WIRS-induced gastric ulcer, we overexpressed ASPA in the bilateral CeA and tested the effects in the WIRS model." (PMID 35281914, 2022). "The overexpression of ASPA in CeA alleviated WIRS-induced gastric ulcer significantly (p < 0.05)." (PMID 35281914, 2022).
lung adenocarcinoma (1 paper, 2025). A carcinoma that arises from the lung and is characterized by the presence of malignant glandular epithelial cells. "ASPA (Aspartoacylase) has recently gained attention for its reduced expression in lung adenocarcinoma, potentially reflecting metabolic dysregulation within tumors." (PMID 40565055, 2025).
ovarian carcinoma (1 paper, 2021). A malignant neoplasm originating from the surface ovarian epithelium. "Surprisingly, GLUL levels, but not ASPA levels (Fig EV5A) in ascitic macrophages also correlated with the stage, indicating the GS represents a specific feature of protumoral macrophages in ovarian cancer." (PMID 34260142, 2021).
Peptic ulcer (1 paper, 2019). The term peptic ulcer refers to acid peptic injury of the digestive tract, resulting in mucosal break reaching the submucosa. "There is no role of babA, homB, aspA, and sabA genes for the development of peptic ulcer in Turkish population." (PMID 31312620, 2019).
prostate carcinoma (1 paper, 2023). A carcinoma that arises from epithelial cells of the prostate gland. "The correlation between ASPA and cancer remains largely unknown, with a lack of evidence demonstrating the key role of ASPA in the progression of prostate cancer and breast cancer." (PMID 37391709, 2023).
temporal lobe epilepsy (1 paper, 2021). A localization-related (focal) form of epilepsy characterized by recurrent seizures that arise from foci within the temporal lobe, most commonly from its mesial aspect. "Similar to this study, increased expression of MOG, PLP1, ABCA2, FA2H, TF, ASPA was demonstrated in high-spiking regions of cortical areas of temporal lobe epilepsy patients." (PMID 34301297, 2021).
cancer (7 papers, 2014 to 2025). A tumor composed of atypical neoplastic, often pleomorphic cells that invade other tissues. "Compared to the non-cancer tissues, the GC tissues had a significantly lower level of ASPA expression (p < 0.05)." (PMID 37391709, 2023). "Both the proliferation and the invasion capacity of GC cancer cell lines found to be altered in the ASPA knockdown and overexpression experiment." (PMID 37391709, 2023). "Aspartoacylase (ASPA) is a gene that plays an important role in the metabolic reprogramming of cancer." (PMID 37391709, 2023). "While one major acetate source providing substrate for ACSS2 is through ubiquitous protein deacetylation reactions, such as histone deacetylation, NAA is another readily available source of acetate in cancer cells that express NAT8L, ASPA, and ACSS2." (PMID 33304273, 2020).
infection (6 papers, 2013 to 2023). The state of being infected such as from the introduction of a foreign agent such as serum, vaccine, antigenic substance or organism. "We further explored the role of aspA in the colonization dynamics of P. multocida during systemic infection by competitive infection of 55-day-old healthy chickens with a 1:1 ratio of C48–1 and the aspA mutant." (PMID 33272193, 2020). "The bacterial loads of the aspA mutant strain in the spleen (209-fold reduction, P < 0.01) and liver (115-fold reduction, P < 0.01) at 24 h post-infection were significantly reduced compared with the parent strain C48–1." (PMID 33272193, 2020). "The aspA mutant was also significantly outcompeted by the wild-type strain in the spleen (263-fold reduction, P < 0.01) and liver (182-fold reduction, P < 0.01) at 72 h post-infection." (PMID 33272193, 2020). "We therefore further studied the function of the aspA gene by constructing aspA mutant strain △aspA::kan and complementary strain C△aspA::kan, and assessed its functions in growth in complex medium and under anaerobic, acid, and iron-limited conditions, and during infection in vivo." (PMID 33272193, 2020). "We used two clinical M serotypes expressing AspA, and their aspA gene deletant isogenic mutants in experiments using adherence assays to respiratory epithelium, macrophage phagocytosis and neutrophil killing assays and in vivo models of respiratory tract colonisation and infection." (PMID 23638083, 2013). "However, knockout mutants in the aspA gene failed to become established (being cleared by 2 days post-infection) and were rendered susceptible to macrophage phagocytosis in vitro." (PMID 23638083, 2013). "AspA is important for the establishment of the infection in an immunocompetent mouse model but not in the chemotherapeutic mouse model, and the lack of AspA also plays an important role in modulating proinflammatory cytokines in vivo." (PMID 37790311, 2023). "An intramuscular route of infection may not reveal the role of aspA in virulence compared to an experiment where chickens are inoculated with P. multocida in a manner that reflects natural transmission such as through the mouth, nose, or conjunctiva." (PMID 33272193, 2020).
tumor (6 papers, 2011 to 2023). "In tumor-bearing murine models, overexpression of ASPA significantly reduced tumor volumes and weights (P < 0.01)." (PMID 37271807, 2023). "In contrast, ASPA knockdown resulted in increased tumor weights and up-regulated expression of PCNA, cyclin D1, N-cadherin, and MMP9 (P < 0.05 or P < 0.01), concomitant with the inhibition of E-cadherin expression (P < 0.01)." (PMID 37271807, 2023). "The western blots presented a similar expression pattern of ASPA in the tumour and non-tumour tissues (p < 0001)." (PMID 37391709, 2023). "Our findings provide novel insights into the tumor-suppressive function of ASPA in PCa and highlight its potential as a prognostic biomarker and therapeutic target for the management of this malignancy." (PMID 37271807, 2023). "Conversely, ASPA knockdown led to increased tumor volumes and weights (P < 0.01), with IHC staining exhibiting a significantly higher number of Ki67-positive cells in the ASPA knockdown group compared to the control." (PMID 37271807, 2023). "The inhibitory role of ASPA in PCa was further confirmed using orthotopic and tumor-bearing mouse models." (PMID 37271807, 2023). "Moreover, orthotopic xenograft models demonstrated that ASPA overexpression led to a decrease in tumor weight (P < 0.01)." (PMID 37271807, 2023). "This research discovered that tumour tissues have lower levels of ASPA expression." (PMID 37391709, 2023). "In our investigation, we have demonstrated that ASPA functioned as a tumor suppressor in PCa." (PMID 37271807, 2023). "As a result, we hypothesised that ASPA may behave as a tumour-promoting factor as GC evolves." (PMID 37391709, 2023). "Based on the finding that ASPA expression does not correlate with tumor NAA, a non‐catabolic role of NAA has been hypothesized (Bogner‐Strauss, 2017)." (PMID 34260142, 2021).
neurodegenerative disease (2 papers, 2016 to 2025). A disorder of the central nervous system characterized by gradual and progressive loss of neural tissue and neurologic function. "CD is an autosomal recessive inherited neurodegenerative disease caused by an aspartoacylase (ASPA) mutation." (PMID 40076831, 2025).
ASPA also shares sentences with these, for which no sentence is quoted: genetic disorder (4 papers); neurological disorder (3); demyelinating disease (2); epilepsy (2); fatty liver (2); lung carcinoma (2); protein misfolding disorder (2); adenosine monophosphate deaminase deficiency (1); Allan-Herndon-Dudley syndrome (1); Alzheimer disease (1); Anxiety (1); astrocytoma (1); autism (1); Birt-Hogg-Dube syndrome (1); breast carcinoma (1); colon tumor (1); demyelination (1); glioblastoma (1); ileitis (1); Leukoencephalopathy (1); liver cancer (1); liver disease (1); Lynch syndrome (1); Macrocephaly (1); major depressive disorder (1); metabolic disease (1); Miller-Dieker lissencephaly syndrome (1); multiple sclerosis (1); neurodevelopmental disorder (1); osteosarcoma (1).
A further 3 diseases each share a sentence with ASPA in 1 paper.